NPPA (natriuretic peptide A)
Diseases named in the same sentence as NPPA in open-access papers (continued):
Sharing a sentence is not in itself a finding about the gene and the disease.
heart failure (continued). "As a means of better understanding the underlying molecular mechanisms of heart failure, much effort has been made to elucidate the mechanisms regulating expression of fetal cardiac genes, including NPPA and NPPB, the genes respectively encoding ANP and BNP." (PMID 36009824, 2022). "The occurrence and development of heart failure are closely related to the disorder of water and electrolyte metabolism, which are mainly modulated by natriuretic peptides A (NPPA) and GMP signaling." (PMID 36034815, 2022). "Additionally, the expression level of heart failure markers was detected in hearts, including natriuretic peptide A (Anp), natriuretic peptide B (Bnp) and beta-myosin heavy chain (β-Mhc)." (PMID 35310994, 2022). "Transcriptome analyses demonstrated that the protective effects of developing heart failure were accompanied by down-regulating of the Natriuretic Peptide A gene expression and by decreasing the concentrations of angiotensin II and atrial natriuretic peptide in plasma." (PMID 34575987, 2021). "First, we assessed whether these 28 WNT-related genes and two well-described heart failure genes—NPPA and NPPB—exhibited differential expression between NF/pRV/RVF separately for both DCM and ICM using Kruskal–Wallis to compare log2fold changes." (PMID 33134326, 2020). "In patients with heart failure, reactivation of NPPA and NPPB is correlated with demethylation of H3K9 at their promoter regions, although a modest increase in H3K27ac could also be observed." (PMID 29302701, 2018). "Natriuretic peptides, particularly NPPA (translated to ANP) and NPPB (translated to BNP), have emerged as valuable predictors of stroke and heart failure, including NT-proBNP." (PMID 40296161, 2025). "Integrating the results of the TBX5-targeted genes and the DEGs in toxicity pathways, we found that the dysregulation of TBX5-targeted genes, TNNT2, NPPA, TTN, ATP2A2, DES and SCN5A, contributed to the development of heart failure and arrhythmia." (PMID 32423033, 2020). "Natriuretic peptide A (NPPA, ANP) and B (NPPB, BNP) have emerged as important candidates for the development of therapeutic agents for heart failure." (PMID 27324127, 2016). "On the other hand, STAT3 activates the transcription regulator GATA4, thereby upregulating the expression of NPPA, MYH7, and MYH6, which interacted with each other to regulate the structure and function of the sarcomere, resulting in heart failure and arrhythmias." (PMID 36034815, 2022). "In addition, in our analysis results, NPPA, NPPB, COL1A2, ASPN, ANKRD1 and CTGF were all confirmed to be closely related to heart failure in dilated cardiomyopathy in various studies." (PMID 34970603, 2021). "Therefore, adding to our study, NPPA gene has been previously identified in GES of cardiac diseases, such as heart failure and dilated cardiomyopathy." (PMID 32670412, 2020). "Of these, the lncRNA NPPA-AS was selected for further investigation which revealed NPPA-AS has a demonstrated influence on the splicing of the natriuretic peptide precursor A (NPPA) gene (present in cardiac hypertrophy and heart failure) and, therefore, has potential CVD involvement." (PMID 27023534, 2016). "NPPA is reactivated in response to cardiovascular disorders and converted to its active form by CORIN, which harbored four circRNAs (validated in atrium and vena cava) and could be potential biomarkers for heart failure." (PMID 28842720, 2017).
Hypertension (163 papers, 2009 to 2026). The presence of chronic increased pressure in the systemic arterial system. "For instance, a meta-analysis involving 4068 individuals revealed that the NPPA gene rs5065 SNP has been linked with hypertension, myocardial infarction, stroke, and coronary artery disease in the Chinese and Han populations." (PMID 39859138, 2025). "NPPA: The rs5068 variant in the Natriuretic Peptide A (NPPA) gene, which encodes atrial natriuretic peptide, offers protective effects against hypertension." (PMID 37965396, 2023). "Here, we aimed to examine the association between NPPA promoter methylation and hypertension in two independent samples of Chinese adults." (PMID 32883357, 2020). "The causality of DNA methylation of the NPPA gene in hypertension development is still unclear and warranted to be further studied." (PMID 32883357, 2020). "The gene-based analysis found that DNA methylation of the 9 CpGs at NPPA promoter as a whole was significantly associated with blood pressure and prevalent hypertension in both samples (all P < 0.05)." (PMID 32883357, 2020). "In conclusion, we demonstrate that hypermethylation at NPPA promoter is associated with a lower level of blood pressure and a lower risk of having hypertension in Chinese adults." (PMID 32883357, 2020). "A similar phenomenon of the association between NPPA promoter methylation and hypertension was observed in the replication sample." (PMID 32883357, 2020). "A recent GWAS identified a hypertension-related SNP rs3753584 located at the NPPA gene which was associated with a higher circulating ANP level." (PMID 32883357, 2020). "Polymorphisms of its coding gene—natriuretic peptide A (NPPA)—have also been associated with the susceptibility to hypertension, stroke, myocardial infarction, and coronary artery disease." (PMID 32883357, 2020). "The rs5068 (A/G) allele in the 3’-UTR of the NPPA gene, that encodes atrial natriuretic peptide (ANP), is also involved in hypertension." (PMID 30445764, 2018). "In a large meta‐analysis of common variants in the NPPA‐NPPB locus, Newton‐Cheh et al13 showed that NPPA polymorphisms (rs5068 and rs198358) were associated with increased BNP and NT‐proBNP as well as ANP levels and a lower risk of hypertension." (PMID 28341776, 2017). "After adjusting for age, sex, BMI and hypertension status, we found that the NPPA rs5063 was significantly associated with reduced risk for ischemic stroke and cerebral hemorrhage in SHINING cohort." (PMID 25144711, 2014). "In the hypertension group, after adjustment for age, sex and BMI, the NPPA rs5063 was associated with ischemic stroke and cerebral hemorrhage." (PMID 25144711, 2014). "Common genetic variants at the NPPA locus that are associated with the higher ANP concentration are also associated with lower blood pressure and reduced risk of hypertension." (PMID 19671135, 2009). "Another study conducted in Chinese Han hypertensive patients also found that CYP2D6∗10 was not in HWE; this might be because CYP2D6∗10, AGTR1 (1166A > C), and NPPA (2238T > C) genes were associated with the development of hypertension." (PMID 38298191, 2024). "For example, a meta-analysis including 4068 individuals revealed that the NPPA gene rs5065 polymorphism might contribute to the occurrence of hypertension." (PMID 32883357, 2020). "Notably, the association of rs5068 located at the NPPA gene with hypertension reached a genome-wide significance with a P value of 1 × 10−8." (PMID 32883357, 2020). "Selection bias may therefore exist in the replication sample and may overestimate the magnitude of the association between NPPA promoter methylation and hypertension." (PMID 32883357, 2020). "It is still unclear whether aberrant methylation at NPPA promoter is a risk factor, consequence, or just an accompanying phenomenon of hypertension." (PMID 32883357, 2020).
Hypertension (continued). "Leveraging an unselected population in the Gusu cohort, we are the first to examine the association between NPPA promoter methylation and hypertension and provide initial evidence for the potential role of NPPA promoter methylation in the pathogenesis of hypertension." (PMID 32883357, 2020). "In addition, it has been noted that in a large-scale prospective study, the A allele of NPPA rs5063 has provided a protective effect for blood pressure progression in 48 months and incident hypertension for the entire follow-up." (PMID 25144711, 2014). "In an angiotensin II-induced hypertension model, offspring of high-fiber-fed mothers exhibited reduced histone H3 acetylation at the natriuretic peptide A (Nppa) promoter, highlighting the intergenerational cardioprotective effects of maternal diet." (PMID 41504275, 2026). "Previous research has shown that NPPA rs5068 functions in blood pressure control and the development of hypertension in the Japanese population, which contrasts with our findings." (PMID 39859138, 2025). "Variants in the NPPA gene, encoding ANP, are associated with increased risks of cardiovascular disease, such as hypertension, stroke, and heart disease." (PMID 36362216, 2022). "Several studies have demonstrated a link of ANP (NPPA), BNP (NPPB), and NPRA (NPR1) polymorphisms with hypertension and CVDs in humans." (PMID 34489721, 2021). "It has been reported that a positive association exists between the polymorphisms of NPPA, NPPB, and NPR1 causing essential hypertension and LHV." (PMID 34489721, 2021). "Our results suggest a potential role of NPPA promoter methylation in the molecular mechanisms of hypertension." (PMID 32883357, 2020). "No study, to the best of our knowledge, has examined the role of DNA methylation at the NPPA gene in hypertension." (PMID 32883357, 2020). "Although we did not have data on circulating ANP in our study, together with prior studies, we believed that DNA methylation of the NPPA gene undoubtedly participated in the molecular mechanisms of hypertension." (PMID 32883357, 2020). "The gene-based analysis found that DNA methylation of the 9 CpGs at NPPA promoter as a whole was significantly associated with SBP, DBP, and prevalent hypertension (all P < 0.05)." (PMID 32883357, 2020). "Among others, the minor allele at rs5068 NPPA variant turned out to be associated with higher ANP levels and with hypertension risk." (PMID 30781751, 2019). "Beyond its hemodynamic effects, riociguat reduced renal and cardiac fibrosis, increased creatinine clearance, decreased atrial natriuretic peptide and left ventricular mass in two independent models of hypertension." (PMID 27590259, 2016). "We further individually tested the association of NPPA rs5063 and MTHFR rs1801133 with ischemic stroke and cerebral hemorrhage stratified with hypertension status." (PMID 25144711, 2014). "After adjustment for age, sex, BMI and hypertension status, the interaction between NPPA rs5063 and MTHFR rs1801133 with ischemic stroke and cerebral hemorrhage was not statistically significant." (PMID 25144711, 2014). "After adjustment for age, sex, BMI and hypertension status, ORs of NPPA rs5063 (95% CI; P value) were 0.69 (0.52–0.90; 0.006) for ischemic stroke and 0.39 (0.19–0.78; 0.007) for cerebral hemorrhage respectively." (PMID 25144711, 2014). "Genetic variation in the genes encoding ANP and BNP i.e. the NPPA-NPPB locus has been associated with variation in NP levels and hypertension." (PMID 24465655, 2014). "Association of specific NPPA variants with increased ANP levels as well as with lower blood pressure and reduced risk of hypertension strongly support the central role of NPPA in the maintenance of blood pressure homeostasis." (PMID 19671135, 2009). "Notably, the link between rs5068 at the NPPA gene and hypertension was significant genome-wide, with a p-value of 1 × 10−8." (PMID 39859138, 2025).
Hypertension (continued). "Some hypertension-related genes exhibited high deletion frequency, including NPPA, ADD1, and INSR." (PMID 35513851, 2022). "Here, we aimed to examine whether DNA methylation, a molecular modification to the genome, of the natriuretic peptide A gene (NPPA), the coding gene of ANP, was associated with hypertension." (PMID 32883357, 2020). "DNA methylation levels at NPPA promoter were decreased in Chinese adults with hypertension." (PMID 32883357, 2020). "Gene network analysis found similar results that the NPPA gene may play a critical role in the pathogenesis of hypertension through varied functions, e.g., circulatory system process, regulation of blood pressure, and blood circulation." (PMID 32883357, 2020). "Hypermethylation at the promoter region of the NPPA gene was associated with a lower risk of prevalent hypertension, independent of behavior and metabolic factors." (PMID 32883357, 2020). "Of note, we reported an association of the –664C > G minor allele located within the NPPA promoter and associated with lower plasma ANP levels, early onset of blood pressure increase, and the predisposition to develop hypertension in a general population from Southern Italy." (PMID 30781751, 2019). "Natriuretic peptide precursor A is the precursor to atrial natriuretic peptide (ANP) before synthesis; NPPA polymorphism may induce myocardial necrosis, hypertension, atrial fibrillation, water and sodium disequilibrium, and heart remodeling." (PMID 29867541, 2018). "Whether and to what extent NPPA promoter methylation accounts for the molecular mechanisms underlying the association between ANP and hypertension still needs more investigation, although hypomethylation of the NPPA gene was found to be associated with an upregulation of the transcripts of ANP." (PMID 32883357, 2020). "Aberrant DNA methylation of the NPPA gene may participate in the mechanisms of hypertension." (PMID 32883357, 2020). "Therefore, the aim of our study was to analyze the associations of NPPA:rs5065 and NPPB:rs198389 polymorphisms in Polish patients with HF with the risk of HF, as well as with cardiovascular phenotypes, including type 2 diabetes mellitus (T2DM), hypertension, left ventricular mass (LVM), and LVEF." (PMID 40429712, 2025). "Other studies showed that ANP/NPPA knocked out mice had hypertrophy and hypertension under both resting and pressured conditions as compared to wild-type control mice." (PMID 34770174, 2021). "Therefore, we examined whether DNA methylation at NPPA promoter, rather than a single CpG site, was associated with hypertension." (PMID 32883357, 2020). "Our results may unravel a molecular mechanism that NPPA promoter methylation may participate in the pathology of hypertension and suggest that simultaneously testing the joint effects of multiple CpG sites is a powerful approach in epigenetic analysis for complicated diseases, e.g., hypertension." (PMID 32883357, 2020). "NPPA (natriuretic peptide precursor A) belongs to the ECM genes in the GO database, whose expression is considered to involve in the familial atrial fibrillation, heart development, and hypertension." (PMID 34616853, 2021). "We, therefore, hypothesized that the NPPA promoter methylation may be a potential molecular modification that regulates ANP expression/excretion and participate in the pathogenesis of hypertension." (PMID 32883357, 2020). "Leveraging two independent samples of Chinese adults, we found for the first time that DNA methylation levels of NPPA promoter were lower in participants with hypertension than those without." (PMID 32883357, 2020). "We found that DNA methylation level of NPPA promoter was more likely to be lower in participants with hypertension than those without." (PMID 32883357, 2020). "Increasing ANP levels, possibly by using miRNA inhibitors (anti-miRs) to interfere with miRNA-mediated repression of NPPA expression, is a promising approach to the treatment of hypertension." (PMID 29698509, 2018).
Hypertension (continued). "Therefore, we hypothesized that aberrant methylation of the NPPA promoter may affect its function and subsequent ANP synthesis and excretion, thereby participating in the pathogenesis of hypertension, but this has not been studied in humans." (PMID 32883357, 2020). "Therefore, we concluded that NPPA rs5063 and MTHFR rs1801133 were associated with cerebral hemorrhage and NPPA rs5063 was marginally associated with ischemic stroke and were not directly associated with hypertension." (PMID 25144711, 2014). "As NPPA has been demonstrated to inhibit NFAT activation, this DS‐induced up‐regulation of NPPA could explain why RCAN1 was not up‐regulated in DS‐treated rats, even though crucial Ca2+‐handling genes (ATP1A2, SERCA2A and PLN) were dysregulated upon DS‐induced hypertension." (PMID 31368189, 2019).
Obesity (52 papers, 2012 to 2026). Accumulation of substantial excess body fat. "Second, five proteins (CCL25, GRIA4, HBEGF, NPPA and RETN) were also considered because they have been reported to be associated with obesity." (PMID 35879730, 2022). "As shown in the obesity → NPPB (Brain natriuretic peptide) or NPPA (Atrial natriuretic peptide) → MI pathway, both natriuretic peptides were belonged to the MI promotors but inhibited by obesity." (PMID 33842562, 2021). "In our study, DPR attenuates obesity‐induced cardiac remodeling during aging, as evidenced by the normalization of heart weight and the suppression of hypertrophic markers, including Cyclin D1, NPPA, and DDB1." (PMID 41549510, 2026). "In addition, the proteins CCL25, GRIA4, HBEGF, NPPA and RETN, which are affected by RNAm-SNPs, have been reported to be related to obesity." (PMID 35879730, 2022).
diabetes (50 papers, 2008 to 2025). "Notably human studies have shown an association of a single nucleotide polymorphism rs5068 on the natriuretic peptide precursor A (NPPA) locus gene with higher levels of circulating ANP and lower likelihood of incident diabetes." (PMID 30016962, 2018). "We genotyped the variant rs5068 within the NPPA locus in 27,307 individuals without known diabetes from the Malmö Diet Cancer Study." (PMID 24586593, 2014). "Since gene variants are inherited randomly and not subject to confounding we aimed to investigate whether the variant rs5068 within the NPPA locus, previously shown to be associated with ANP levels in plasma, also is associated with incident diabetes." (PMID 24586593, 2014). "Expression of atrial natriuretic peptide and fibrosis markers, all indicative of advanced diabetes, were not altered by the HFD regime." (PMID 34265467, 2021). "Our findings concur with a recent report of decreased NPPA mRNA and protein levels at 3 months but not 1 month of STZ-diabetes in rats." (PMID 18554398, 2008).
myocardial infarction (49 papers, 2007 to 2026). Gross necrosis of the myocardium, as a result of interruption of the blood supply to the area, as in coronary thrombosis. "The troponin genes (TNNC1, TNNT2, TNNI3), the creatine kinase gene (CKM), and the brain natriuretic peptide gene (NPPA) are recognized biomarkers of myocardial infarction." (PMID 40433126, 2025). "Epidemiologic studies confirmed that common NPPA (the gene encoding ANP) variants rs5065/rs5063 are associated with an increased risk of stroke and a higher prevalence of myocardial infarction in the general population." (PMID 35956306, 2022). "Based on a correlation coefficient of 0.70, it was concluded that the percentage change in the size of the left atrium could reliably predict the percentage change in atrial natriuretic peptide after an acute myocardial infarction." (PMID 20972516, 2010). "Notably, JUP and VDAC3 exhibited a high correlation with myocardial infarction biomarkers; however, JUP also demonstrated a significant correlation with TNNC1, TNNT2, TNNI, CKM, and NPPA (P < 0.05)." (PMID 40433126, 2025).